SDC1 (syndecan 1)
Diseases named in the same sentence as SDC1 in open-access papers (continued):
Sharing a sentence is not in itself a finding about the gene and the disease.
breast carcinoma (continued). "Whereas high Sdc-1 expression in mammary carcinoma is related to poor prognosis, low Sdc-1 expression in cervical carcinoma is associated with poor differentiation and poor prognosis." (PMID 35155241, 2022). "Combination of 6 protein markers (Adipsin, Leptin, Syndecan-1, Basic fibroblast growth factor, Interleukin 17B and Dickopff-3) resulted in 65% sensitivity and 80% specificity in detecting breast cancer." (PMID 34997107, 2022). "SDC1 regulates ECM fiber organization in breast cancer stromal fibroblasts and thus is involved in cell motility." (PMID 34981672, 2022). "We also found that SDC1 expression varies widely among different types of breast cancer, with Her2-enriched exhibiting among the highest levels of expression." (PMID 36277284, 2022). "SDC1 also has a pro-metastatic role in the mouse model of breast cancer brain metastasis (BCBM), by which SDC1 regulates cytokines of the BBB and tames BC cells across the BBB." (PMID 35793235, 2022). "Other described interactions include the association between syndecan-1, the insulin-like growth factor-1 receptor (IGF1-R) and αvβ3 or αvβ5 in both human mammary carcinoma cells and endothelial cells undergoing angiogenesis." (PMID 33669066, 2021). "A third study showed that there was a growth promoting loop between breast cancer cells and the stromal compartment, which was dependent on heparan sulfate-bearing syndecan-1." (PMID 33921767, 2021). "In the breast cancer field, for example, shed syndecan-1 promotes invasive behavior, in a manner sensitive to the MMP inhibitor, TIMP1, and also triggers loss of E-cadherin." (PMID 33921767, 2021). "To study a possible cooperative effect of Sdc-1 and HA in breast cancer angiogenesis, we analyzed the expression of the angiogenesis-related genes VEGF, PDGF, ANG-1, and IL-8 by RT-qPCR." (PMID 34070901, 2021). "While we previously showed that miR-10b is expressed depending on the estrogen receptor status in breast cancer cells, Sdc-1-dependent miR-10b regulation was observed in both ER-positive and -negative model cell lines in our study." (PMID 34070901, 2021). "Subsequently, we evaluated the impact of Sdc-1 expression on the prognosis of the patients with breast cancer." (PMID 34070901, 2021). "A further study showed that treatment with synstatin, a peptide inhibitor that disrupts the interaction of Sdc-1 with αvβ3 and αvβ5 integrins, impairs angiogenesis in vitro and in a mouse model of breast cancer." (PMID 34066023, 2021). "In breast cancer, Sdc-1 along with E-cadherin and c-met constitutes an expression signature associated with angiogenic and lymphangiogenic factors in ductal carcinoma in situ." (PMID 34066023, 2021). "SDC1 levels in pre-chemotherapy breast cancer biopsies correlate with decreased response to treatment with cyclophosphamide and epirubicin." (PMID 33494442, 2021). "A recent study involving breast cancer patients demonstrates that syndecan-1 levels in its soluble form increased compared to healthy patients." (PMID 33669066, 2021). "Our study on over 3000 patients firmly establishes a prognostic role for the TF pathway in breast cancer and provides a novel link to Sdc-1." (PMID 34066023, 2021). "The expression of this fragment enhances the cell proliferation of BT-549 human breast cancer cells even in the presence of endogenous SDC1." (PMID 34113616, 2021). "Secreted growth factors by breast cancer cells have been shown by our laboratory to affect the expression of the proteoglycan syndecan-1 in human breast stromal fibroblasts." (PMID 33924197, 2021). "Increased cell migration, invasion and MMP production are positively correlated with the co-localization of β1 integrin and SDC-1 in breast cancer cells." (PMID 35118073, 2021). "To evaluate the impact of Sdc-1 downregulation on HA synthesis and function, we silenced Sdc-1 employing siRNA knockdown (KD) in the breast cancer cell lines MCF-7 (ER+, luminal subtype) and MDA-MB-231 (triple-negative, basal subtype)." (PMID 34070901, 2021).
breast carcinoma (continued). "Our data suggest that Sdc-1 knockdown has a differential effect on HA metabolism in the breast cancer cell lines MCF-7 and MDA-MB-231, and impacts on the stem phenotype, cell survival, and angiogenic factor expression and secretion." (PMID 34070901, 2021). "The functional significance of syndecan-1 expression in the setting of the tumor stroma of breast cancer remains to be elucidated." (PMID 34952631, 2021). "We have reported that Sdc-1 is overexpressed and governs the cancer stem cell properties of triple-negative inflammatory breast cancer cells." (PMID 34066023, 2021). "In a much older study, for example, syndecan-1 had a lysosomal distribution in poorly differentiated breast carcinoma." (PMID 33921767, 2021). "In breast cancer for example, SDC1 has been suggested to act both as a regulator of cancer stem cell (CSC) phenotype and as a modulator of lymphocytes, in particular of T helper cells, depending on the subtype of the disease." (PMID 33494442, 2021). "targeted Syndecan-1 expression in MCF-7 breast cancer cells and found ansubsequent increase of OPG leading to inhibition of osteoclastogenesis." (PMID 33239699, 2020). "First, we validated its effectiveness in our own hands to block MDA-MB-231 breast cancer cell binding to vitronectin, an interaction that specifically requires SDC1-ITGαvβ3 complexes." (PMID 32760722, 2020). "Sdc-1 is also more abundant in the ER-negative tumors, suggesting that its expression marks this more aggressive breast cancer phenotype." (PMID 33330449, 2020). "The authors found that proteolytic conversion of syndecan-1 from being membrane-bound to a soluble form switched breast cancer cells from a proliferative to an invasive phenotype." (PMID 33163489, 2020). "There is also evidence that SDC1 can promote the migration of breast cancer cells across the blood–brain barrier by regulating the expression of cytokines, thus promoting brain metastasis." (PMID 33194424, 2020). "In line with this, Sdc-1 expression in stromal fibroblasts induces rearrangement of the collagen fibers, allowing breast cancer cells to adhere and extravasate more efficiently." (PMID 33330449, 2020). "Many HSPGs and their associated enzymes have been associated with the disease, with both SDC1 and SDC4 showing strong involvement with breast cancer." (PMID 32398079, 2020). "In in vitro studies, a potential role for syndecan-1 in modulating breast cancer brain metastasis has been identified." (PMID 33163489, 2020). "SDC1 is known to have a role in various cancers, including breast cancer through its role in cell adhesion, migration and proliferation." (PMID 32398079, 2020). "Hsa-miR-122-5p was reported to suppress syndecan-1 expression, inhibiting breast cancer cell mobility." (PMID 32466456, 2020). "Downregulation of this PG expression resulted in the reduction of stemness-related phenotypic characteristics of MDA-MB-231 cells, indicating that syndecan-1 enhances EMT in breast cancer." (PMID 32847060, 2020). "In support of this, orthotopic injection of aggressive murine mammary tumor cell lines into Sdc-1–/– mice prevented lung metastasis compared to wild-type animals." (PMID 33330449, 2020). "It has been reported that the expression of Sdc1 is lower in highly metastatic cells and leads to an increased activation of β1-integrins and focal adhesion kinase, which contributes to breast cancer cell adhesion and invasion from the primary tumor." (PMID 31949431, 2019). "Sdc-1 expression is upregulated in human breast carcinoma tissue, and its overexpression is correlated with cancer aggressiveness and poor prognosis." (PMID 31145753, 2019). "In breast carcinoma, the differential expression and molecular functions have been assigned to Sdc-1 in the context of its stromal/cancer cell expression and/or its membrane-bound/shedding forms." (PMID 31145753, 2019).
breast carcinoma (continued). "One of the key molecules that are implicated in the modulation of inflammatory cytokines and chemokines, as well as the progression of breast carcinoma, is the heparan sulfate (HS) proteoglycan Syndecan-1 (Sdc-1; CD138)." (PMID 31145753, 2019). "In breast cancer, Sdc1 generally acts as a promoter of tumor growth and progression via multiple mechanisms of action." (PMID 29976229, 2018). "The expression of SDC1 protein and hsa-miR-122-5p were examined in two breast cancer cell lines, MCF-7 and MDA-MB-231, with western blotting and PCR." (PMID 29963269, 2018). "Gotte and collaborators noted a relationship between intensity of syndecan-1 immunostaining in pre-chemotherapy breast cancer biopsies and decreased response to treatment with cyclophosphamide and cisplatin." (PMID 30413079, 2018). "In summary, we show that Sdc1 expression is induced in stromal fibroblasts in the lung metastatic microenvironment and that host Sdc1 is required for efficient outgrowth of mammary carcinoma metastases." (PMID 29976229, 2018). "We used the ESTIMATE algorithm to correlate the extent of stromal cells with expression of IL-34, CSF-1, CSF-1R, PTPRZ1, and syndecan-1 in breast cancer tissue from the TCGA breast cancer dataset." (PMID 29796177, 2018). "It was also reported that lower SDC1 expression was correlated with higher cell mobility of breast cancer cells." (PMID 29963269, 2018). "In summary, Sdc1 is induced in the lung microenvironment after mammary carcinoma cell dissemination and promotes outgrowth of metastases in a temperature-dependent manner." (PMID 29976229, 2018). "In this study, we proposed a experimental workflow to investigate potential microRNAs that regulate SDC1 expression and affect breast cancer cell mobility." (PMID 29963269, 2018). "In contrast, syndecan-1 ectodomains in conditioned medium from breast cancer cells played a critical role in the stimulation of osteoclastogenesis in human peripheral blood mononuclear cells." (PMID 30389911, 2018). "The presence of exosomal miRNA-122-5p secreted from liver cells would influence breast cancer mobility through SDC1 downregulation, that a mechanism affecting the metastasis of breast cancer was proposed." (PMID 29963269, 2018). "Next, we examined the prognostic effect of CSF-1, CSF-1R, PTPRZ1, and syndecan-1 expression in the breast cancer TCGA dataset by generating Kaplan–Meier survival curves split in high (top 50%) and low (bottom 50%) gene expression." (PMID 29796177, 2018). "A strategy to screen potential miRNAs regulating SDC1 expression in breast cancer cells was established." (PMID 29963269, 2018). "Stromal fibroblasts in the metastases expressed Sdc1, mirroring Sdc1 induction in primary human breast carcinomas." (PMID 29976229, 2018). "According to the GEO data, progression of breast cancer was correlated with upregulation of SDC1 expression." (PMID 29963269, 2018). "Those suggested the involvement of SDC1 in initial stages of transformation and contribution to the malignancy of breast cancer cells." (PMID 29963269, 2018). "This mesenchymal induction is recapitulated during malignant progression, when Sdc1 expression is observed in stromal fibroblasts in a variety of carcinoma types, including carcinoma of the breast." (PMID 29976229, 2018). "Here we show that host Sdc1 is required for efficient metastasis of mammary carcinoma cells and that the HSPG acts by enhancing the outgrowth of metastatic lesions." (PMID 29976229, 2018). "Sdc1 overexpression in human breast carcinoma correlates with a proliferative state and poor prognosis." (PMID 29976229, 2018). "In 2D and in 3D co-culture models, fibroblast-derived Sdc1 promotes breast carcinoma cell proliferation via paracrine pathways." (PMID 29976229, 2018). "HSPGs are known to control invasion of breast cancer cells; particularly syndecan 1 and 4, upregulate the formation of FGF-2/HSPG/FGFR-1 invasion complex in MCF7 breast cancer cells." (PMID 29566097, 2018).
breast carcinoma (continued). "For example, stromal SDC1 that is released into the tumor microenvironment promotes breast carcinoma growth by enhancing FGF2 signaling." (PMID 30197623, 2018). "The suppression of syndecan-1 expression by miR-122-5p or shRNAs against syndecan-1 increased breast cancer cell mobility; while overexpression of syndecan-1 inhibited cell mobility." (PMID 29963269, 2018). "Altered syndecan-1 expression has been observed in several cancer cells, including colon carcinoma, glioblastoma, breast cancer and ovarian cancer." (PMID 30135409, 2018). "First, we analyzed GEO data for SDC1 expression and miRNA profiling of clinical samples from breast cancer patients." (PMID 29963269, 2018). "Our results indicated that the liver-derived exosomes increased the mobility of breast cancer MCF-7 cells though SDC1 downregulation mediated by exosomal miR-122-5p." (PMID 29963269, 2018). "In conclusion, our results suggested the downregulation of SDC1 by miR-122-5p or liver-cell-derived exosomes would enhance breast cancer cell mobility." (PMID 29963269, 2018). "In further, miR-122-5p was enriched in liver cell-derived exosomes that was able to suppress syndecan-1 expression and increase cell mobility in breast cancer cells." (PMID 29963269, 2018). "On the other hand, syndecan-1 stimulated by peroxisome proliferator receptor activator gamma acts as a tumor suppressor, triggering the apoptosis of breast cancer cells." (PMID 30135409, 2018). "In this study, we analyzed available Gene Expression Omnibus (GEO) data from patients with breast cancer to search potential miRNAs regulating SDC1 expression." (PMID 29963269, 2018). "Previous work by our group and others has shown that Sdc1 is induced in stromal fibroblasts of breast carcinomas in both humans and in mice and that stromal Sdc1 can stimulate tumor growth and angiogenesis and create an invasion-permissive microenvironment." (PMID 29976229, 2018). "Stromal fibroblast-derived Sdc1 participates in paracrine growth stimulation of breast carcinoma cells and orchestrates stromal extracellular matrix fiber alignment, thereby creating a migration and invasion-permissive microenvironment." (PMID 29976229, 2018). "This is relevant because it ascribes a role to Sdc1 at a critical transition step during the natural history of breast cancer." (PMID 29976229, 2018). "Sdc1 expression is induced in stromal fibroblasts of primary mammary carcinomas in mice and in humans." (PMID 29976229, 2018). "The induction of Sdc1 expression in stromal fibroblasts triggers a reciprocal paracrine signaling loop that stimulates mammary tumor growth in vitro and in vivo." (PMID 29976229, 2018). "Kaplan-Meier Plotter and bc-GenExMiner were performed to identify the prognostic roles of SDC1 in breast cancer." (PMID 29340066, 2017). "We have previously shown that Syndecan-1 is a modulator of breast cancer stemness in MDA-MB-231 and MCF-7 cells." (PMID 28270211, 2017). "In this study, we evaluated the significance of SDC1 mRNA in human breast cancer using Oncomine microarray datasets." (PMID 29340066, 2017). "Since colony and spheroids formation are unique properties for tumorigenesis and self-renewal of CSCs, we evaluated the influence of Syndecan-1 on this process in breast cancer cell lines in vitro." (PMID 28270211, 2017). "Dysregulated expression and a potential role of Syndecan-1 as a modulator of cell proliferation and invasive growth have been demonstrated in different tumor entities including breast cancer." (PMID 28270211, 2017). "To further explore the potential regulation of SDC1 in breast cancer, we performed data mining in breast cancer cohort using cBioPortal." (PMID 29340066, 2017). "In particular, higher expression of SDC1 has been correlated with poorer prognosis for breast cancer patients and correlated with more malignant and higher grade breast cancer tissues." (PMID 29340066, 2017).
breast carcinoma (continued). "Taken together, this proves the efficacy of Syndecan-1 targeting in dampening the inflammatory signaling mediated by NFκB or STAT3 in the two cellular models of different breast cancer subtypes." (PMID 28270211, 2017). "It has been proposed that this stromal SDC1 overexpression provides a favorable environment for breast cancer cells' proliferation and migration, as well as angiogenesis, and represents a marker of poor prognosis." (PMID 27434331, 2016). "On the other hand, medium conditioned by the low-invasive MCF-7 breast cancer cells was unable to provoke any SDC1 upregulation." (PMID 27434331, 2016). "Other studies have shown that miR-10b induces invasion of breast cancer through targeting E-cadherin, and Syndecan-1." (PMID 27756250, 2016). "Studies using an in vitro breast cancer model also suggest that syndecan-1 participates directly in tumor cell spreading and adhesion." (PMID 26869927, 2016). "It has already been proposed that the upregulation of SDC1 in mouse stromal fibroblasts can be achieved only by highly invasive human breast cancer cells (MDA-MB-231), and that this effect was due to a direct cell-cell contact and not to soluble factors." (PMID 27434331, 2016). "Studies revealing the negative regulation of syndecan-1 by miR-10b and its pro-invasive consequences in human breast cancer cells, reported syndecan-1 as a new regulatory target of miR-10b." (PMID 26869927, 2016). "The shift of syndecan-1 expression from the epithelium to the stroma is a poor prognostic factor in breast cancer and PDAC." (PMID 27776346, 2016). "We also studied the role of the paracrine interactions with human breast cancer cells in SDC1 overexpression in fibroblasts and of the intracellular signaling pathways involved." (PMID 27434331, 2016). "Syndecan-1 (SDC-1) modulates β-integrin- and interleukin-6-dependent breast cancer cell adhesion and migration, and its overexpression in human fibrosarcoma cells leads to increased proliferation and migratory ability." (PMID 26516869, 2015). "For example, in breast cancer overexpression of wild type syndecan-1 increased proliferation, but overexpression of constitutively shed syndecan-1 inhibited it." (PMID 26420915, 2015). "For example, miR-10b promotes breast cancer cell invasion and metastasis by targeting syndecan-1 (SDC1) in MDA-MB-231 and MCF-7 cells." (PMID 26377202, 2015). "It was also shown that shed syndecan-1 and predominantly its HS chains from stromal fibroblasts were required for breast carcinoma angiogenesis and growth of breast cancer cells was stimulated by shed syndecan-1 via activation of FGF-2." (PMID 26420915, 2015). "This fiber organization is dependent on syndecan-1 presence and is fundamental for the attachment and migration of breast carcinoma cells." (PMID 26558271, 2015). "In another study, SDC1 expression was detected in approximately 70% of breast cancer cases and found to correlate with tumor grade." (PMID 26293675, 2015). "In a breast cancer cell line overexpression of wild type syndecan-1 increased cell proliferation, whereas overexpression of constitutively shed syndecan-1 had the opposite effect." (PMID 26420915, 2015). "The work by Beauvais and colleagues shows that synstatin, a peptide derived from syndecan-1 active core protein, has antiangiogenic properties in vivo and in vitro, in addition to decreasing mammary carcinoma formation in nude mice." (PMID 26558271, 2015). "Studies from an in vitro breast cancer model have also suggested that syndecan-1 directly participates in tumor cell spreading and adhesion." (PMID 26420915, 2015). "Conversely, syndecan-1 expression in breast carcinoma is an indicator of poor prognosis, particularly where it is stromal." (PMID 25623282, 2015). "In breast carcinoma, syndecan-1 can promote cell spreading and adhesion to extracellular matrix with subsequent inhibition of cell invasion." (PMID 25623282, 2015).